BRCA2 (BRCA2 DNA repair associated)
Diseases named in the same sentence as BRCA2 in open-access papers (continued):
Sharing a sentence is not in itself a finding about the gene and the disease.
cancer (continued). "Inhibiting RAD52 induces synthetic lethality in many cancer cells with defective DNA repair-related proteins, such as BRCA1, BRCA2, PALB2, XAB3, and RAD51 paralogues (i.e., RAD51B, RAD51C, RAD51D, XRCC2, XRCC3)." (PMID 36980703, 2023). "Expression of the BRCA2 and XPD genes in tumour tissue of HNSCC patients declined progressively as the cancer stage advanced, was reverse that of the NAT, but was mirrored by the expression in the blood." (PMID 37113717, 2023). "The last cluster presents strong ‘two-hit’ preferences in a pan-cancer analysis as well as in single cancer types and includes two classical CPGs (BRCA1 and BRCA2) and 19 OMIM genes." (PMID 38143269, 2023). "In summary, we discussed various aspects of R-loops in cancer, specifically focusing on their interplay with DNA repair proteins such as BRCA1, BRCA2, and ATR." (PMID 37108225, 2023). "Normal cells are repaired when damaged through HR, but cancer is fatal when PARP-1 is suppressed because the important proteins for HR, BRCA1 and BRCA2, are broken." (PMID 36902170, 2023). "This patient did not have a pre-PARPi sample available to ascertain if the variant was acquired during PARPi treatment and it is unclear what the implication of this mutation might be for resistance, rather than cancer inception, particularly in the context of a germline BRCA2 mutation." (PMID 38072854, 2023). "These 1,670 genes involved well-established cancer-related genes, including MYC, MYB, BRCA2, ERCC4, and MET for s1 subtype and TERT, BCL2, and SUZ12 for s3 subtype." (PMID 36731467, 2023). "The expression of BRCA2 and XPD in the tumour tissue of HNSCC patients decreased with an increase in the stage of cancer." (PMID 37113717, 2023). "Three high-risk MDS cases (1.2%) displayed chromothripsis involving exclusively chromosome 13 and affecting some cancer genes: FLT3, BRCA2 and RB1." (PMID 35328739, 2022). "Nevertheless, α-hederin, andrographolide, apigenin, asiatic acid, auricularic acid, and sinularin successfully docked with BRCA1, BRCA2, and MDR1 proteins as these compounds have the activity for inhibiting cancer." (PMID 35837379, 2022). "High levels of cancer worry (≥ 14) were identified in 320 women pre-surgery: 57% of the BRCA1-PV and 58% of the BRCA2-PV carriers." (PMID 34997316, 2022). "Although the altered expression of YTHDC1 has been linked with m6A modification machinery and the effect on oncogenic factors, such as BRCA2 or PGR, it has yet to be addressed how YTHDC1 affects splicing or export in cancer cells." (PMID 35563766, 2022). "In our study, of the six women with clinically-detected PV in BRCA2, three underwent BM and BSO at the time of diagnosis and remain cancer free." (PMID 36091166, 2022). "It has been demonstrated that reversion mutations restoring the native reading frame of the genes can occur in BRCA1-, BRCA2-, PALB2-, RAD51C-, or RAD51D-mutant cancers." (PMID 35326571, 2022). "Twelve months post-surgery, median cancer worry was 12 (IQR 10; 15) for both BRCA1-PV and BRCA2-PV carriers." (PMID 34997316, 2022). "We used data from 3,184 BRCA1 and 2,157 BRCA2 families in the Consortium of Investigators of Modifiers of BRCA1/2 to estimate age-specific relative (RR) and absolute risks for 22 first primary cancer types adjusting for family ascertainment." (PMID 35077220, 2022). "In our full cohort, patients were at greater risk of carrying PV/LPV when risk prediction estimates were greater than 10.0% (for BRCA1) or when presenting three or more relatives with cancer (for BRCA1 and BRCA2)." (PMID 36329109, 2022). "On the other hand, cancer cells belonging to C0, C1, and C4 had lower expression levels of HR-related genes, including BRCA1 and BRCA2." (PMID 35892844, 2022). "Frequency exceeding 1% was seen for several other cancer types (2 cancer types for BRCA1, 4 cancer types for BRCA2)." (PMID 35420638, 2022).
cancer (continued). "We have claimed from the overall studies that α-hederin, andrographolide, apigenin, asiatic acid, auricularic acid, and sinularin will be the best conformer for BRCA1, BRCA2, and MDR1-conduced cancer for the future researchers." (PMID 35837379, 2022). "Moreover, frequency of rearrangements at MiDAS sites identified in BRCA2-deficient cells was markedly higher in the tumors with BRCA2 mutations than the tumors with wild-type BRCA2, supporting the premise that TRCs and R-loops drive genomic instability in human cancers lacking HR." (PMID 36002001, 2022). "HSF2BP-BRCA2 interaction occurs within Gly2270 and Thr2337, a region between the BRC repeats and the DNA binding domain of BRCA2 that does not harbor known cancer-associated mutations, suggesting that this region may have a specific function in reproduction rather than in cancer pathogenesis." (PMID 35734584, 2022). "Among the interface genes in the Her2+_TNBC module, the known cancer-related genes are mostly DNA repair genes, such as BARD1, BRIP1, BRCA1, BRCA2, FANCA, FANCC, FANCD2, and FEN1." (PMID 35992864, 2022). "Carrier frequency for females and males in each cancer type was significantly correlated for BRCA1 and BRCA2 (eFigure 5 in the Supplement)." (PMID 35420638, 2022). "Although in the clinics, PARP inhibitors have been used to treat cancers with DSB repair defects, such as BRCA1 and BRCA2 defect cancers, the drug resistance to PARP inhibitors is now a major problem facing the clinic." (PMID 35883563, 2022). "If the attenuations in the PRS effect size are real, they would result in a smaller range of cancer risks for BRCA1 and BRCA2 carriers compared with using the PRS effect sizes estimated from general population data." (PMID 34320204, 2022). "Three months post-surgery, median cancer worry declined to 13 (IQR 10; 14) for BRCA1-PV and to 12 (IQR 10; 16) for BRCA2-PV carriers." (PMID 34997316, 2022). "Cancer worry was related to time since BRCA1/2-PV diagnosis and being before or within the guideline age for RRSO (BRCA1: 35–40 years and BRCA2: 40–45 years)." (PMID 34997316, 2022). "Median cancer worry level before surgery (RRSO or RRS) was 14 (interquartile range (IQR) 12; 16) for BRCA1-PV and 14 (IQR 12; 18) for BRCA2-PV carriers." (PMID 34997316, 2022). "Persistently, high levels of cancer worry (≥ 14 at all three time points) were found in 106 (22%) BRCA1/2-PV carriers (55 BRCA1, 51 BRCA2)." (PMID 34997316, 2022). "Overall, the six genes that had PVs with prevalences greater than one percent for any patient cohort (ATM, BRCA1, BRCA2, CHEK2, CDKN2A and FANCA) comprise a heterogenous group of genes that reflect the complexity of this cancer." (PMID 34255164, 2021). "More studies are needed to understand how SYCP3 interacts with both BRCA2 and RAD51 and the impact on the BRCA2-RAD51 interactions in cancer cells and meiotic cells." (PMID 34440403, 2021). "These approaches identified several oncogenes, including KRAS, CREBBP, PTEN, and BRCA2, as SDL genetic partners of EXT1, highlighting its potential clinical relevance in different cancers." (PMID 33962942, 2021). "We collected a total of 335 BRCA variants derived from Taiwanese population, including 164 from general population, 126 from the Taiwanese cancer patient cohort, and 45 (19 in BRCA1 and 26 in BRCA2) from both groups." (PMID 34235180, 2021). "While such cancer cells subsequently show cell death, the normal cells, which have normal BRCA1 and BRCA2 tumor suppressor genes, carry out homologous recombination repair and escape death." (PMID 34070839, 2021).
cancer (continued). "While a subset of these cancers classified as heterozygous BRCA1/2 loss may have inactivated the second allele by methylation, it is notable that environmental and endogenous genotoxins such as aldehydes have been shown to induce BRCA2 haploinsufficiency and consequent genome instability." (PMID 34877933, 2021). "We identified 35 genes that were more frequently altered in HS/CB tumors versus corresponding TCGA cohorts; of which, 8 genes (PREX2, BIRC6, CNTNAP2, PTPRB, GRM3, ANKRD11, BRCA2, and TET3) are listed on the OncoKB Cancer Genes catalogue." (PMID 34446728, 2021). "Here, we found that LRRK2 is required for the interaction of RAD51 and BRCA2, which is responsible for the recruitment of RAD51 to DNA damage sites in LRRK2–high‐expression cancer cells." (PMID 33784003, 2021). "Among 1,627 participants (95.2% with cancer), we detected 236 (14.5%) BRCA PVs; 160 BRCA1 (31% CNVs); 76 BRCA2 PV frequency varied by country: 26% Brazil, 9% Colombia, 13% Peru, and 17% Mexico." (PMID 34413315, 2021). "Compared to patients without CPGs, distinct clinical phenotypes including the onset age, family and personal cancer history, and pathological features have been found in patients with BRCA1, BRCA2, and other CPGs." (PMID 34336698, 2021). "This translational work is typically designed to investigate clinically relevant subsets of cancer, such as platinum sensitive or platinum resistant tumors, or in PDX models with specific tumor genotypes such as BRCA1- or BRCA2-mutant models." (PMID 33850213, 2021). "In total, 78 of the 448 (17.4%) families had at least one VEO cancer case (BC and/or OC): 15% of BRCA1 families included a VEO-BC case and 8% a VEO-OC case, with 9% and 2%, respectively, for BRCA2 families." (PMID 34356116, 2021). "The overall incidence of cancer for our study cohort was 1·9%, which is similar to the 2·4% reported in the BRCA1 and BRCA2 cohort of IMPACT and lower than the 4·3% of men diagnosed in the first screening round of the ERPSC." (PMID 34678156, 2021). "However, even with these reservations regarding the localizer model, we fully expected the HSF2BP-binding domain of BRCA2 to be essential for meiotic HR, because it is conserved, and no somatic function could be assigned to it by several previous studies in human cancer cells." (PMID 34326328, 2021). "Therefore, it is essential to identify the overlap between participants of the both studies by linking the two data sources, which will allow setting up studies evaluating simultaneously genetic and non-genetic factors modifying cancer risk of carriers of a BRCA1 or BRCA2 mutation." (PMID 34325649, 2021). "Given the function of BRCA1 or BRCA2 in HR repair and maintaining replication fork stability, multiple mechanisms are involved in resistance to PARP inhibitors and cancer cell survival." (PMID 34063568, 2021). "In the Korean general population in gnomAD (non-cancer, v.2.1.1, 1887 subjects), 5 different BRCA1 PLPVs in 7 carriers and 6 different BRCA2 PLPVs in 7 carriers were found." (PMID 34063308, 2021). "Thus, abnormally high replication rates caused by β-catenin accumulation in BRCA2-deficient cells are likely to represent a major source of DNA damage and an important contributing factor to the synergistic effect of oncogene activation and BRCA1/2 abrogation on suppressing cancer cell viability." (PMID 34389725, 2021). "For example, BRCAPRO, available in the BayesMendel R package, considers two cancers (breast and ovarian) and two genes (BRCA1 and BRCA2)." (PMID 34406119, 2021). "BRCA1/BRCA2 are exceptions with an OR > 10 for BRCA, but also show more moderate OR for other cancer types." (PMID 32471518, 2020).
cancer (continued). "After lncRNA POU6F2‐AS2 knockdown, tumour shrinkage was observed, and the expression of cancer resistance‐related gene (P‐gp, MRP2 and BRCA2) was down‐regulated, indicating lncRNA POU6F2‐AS2 knockdown enhanced sensitivity of 5‐FU." (PMID 32100443, 2020). "Cancers in women with BRCA1 and BRCA2 PVs were smaller overall with 75.0% and 85.4% being ≤20 mm, respectively, reflecting the benefits of MRI screening." (PMID 33317064, 2020). "Soon after the discovery of BRCA1 and BRCA2 over 20 years ago, it became apparent that not all hereditary breast and/or ovarian cancer syndrome families were explained by germline variants in these cancer predisposing genes, suggesting that other such genes have yet to be discovered." (PMID 32726901, 2020). "Cancers occurring among BRCA1 carriers are more frequently classified as medullary, whereas histological subtypes among BRCA2 carriers tend to be more heterogeneous." (PMID 33302444, 2020). "The known genotypes of these patients are either FANCD1 (BRCA2) or FANCN (PALB2), in whom cancer usually occurs in the first decade of life." (PMID 33371494, 2020). "Several reports suggest that alternative splicing of specific genes, such as BRCA1, BRCA2, BARD1, or ERCC1, can impact on the response of cancer cells to PT and some studies also suggest that this correlates with PT resistance in human cancer." (PMID 32332923, 2020). "Like APE2, PCNA, BRCA2 and XRCC1 were also significantly upregulated in all cancer types except prostate." (PMID 32111912, 2020). "Rad51 works in conjunction with breast cancer 1 and 2 proteins (BRCA1 and BRCA2) and BRCA2 molecular chaperones to replace RPA and forms filaments on the DNA." (PMID 31263478, 2019). "Detection of a BRCA1 or BRCA2 pathogenic variant triggers several clinical management actions, which may include increased surveillance and prophylactic surgery for healthy carriers or treatment with the PARP inhibitor therapy for carriers diagnosed with cancer." (PMID 31013702, 2019). "In addition, as many cancers have dysregulated DNA repair pathways, inactivation of the p97–ATX3 complex might be a promising strategy to induce synthetic lethality in those cancers where the HR pathway is inactivated, such as BRCA2‐deficient cancers." (PMID 31613024, 2019). "This indicates that both the interaction with BRCA1 and BRCA2 is crucial for PALB2’s function in controlling G2/M-phase progression following DNA damage, which is in accordance with observations in human cancer cells." (PMID 31757951, 2019). "However, women carrying BRCA2 mutations show clinical courses with better prognoses than those carrying BRCA1 mutations, in terms of a longer time to first relapse as well as fewer relapses, but both carriers showed higher survival rates than expected for the stage and grade of their cancers." (PMID 30119676, 2018). "Three of the pan-cancer PTV-ALFRED genes (BRCA1, BRCA2, and ATM) and all four individual cancer type PTV-ALFRED genes were individually significantly enriched for rare PTVs in cases versus controls (nominal P < 0.05)." (PMID 29973584, 2018). "This rise was due to alterations at a low percentage in genes with proven predictive value in the context of approved anti-cancer drugs (e.g., EGFR, BRAF, ERBB2, BRCA1, BRCA2, RET, ALK) in all cancer types." (PMID 29544535, 2018). "However, a study performed in mouse cells deleted for the COOH terminus of BRCA2 (amino acids 3140–3328) and irradiated with γ-radiation shows that the deletion of BRCA2 could accelerate cell proliferation and stimulate cancer by defective MmRadSl-mediated DNA repair." (PMID 29346284, 2018). "BRCA1 (MIM# 113705) and BRCA2 (MIM# 600185) are tumor suppressor genes and their inactivation promotes cancer development." (PMID 29460995, 2018).
cancer (continued). "The gene expression levels of classic molecular cancer players such as fibroblast growth factor receptor (FGFR) 2, breast cancer (BRCA) 1, BRCA2 and estrogen receptor (ESR) 1 were evaluated." (PMID 28945747, 2017). "Rad51 nucleofilament assembly requires the help of mediator proteins, such as breast cancer 1 and 2 (BRCA1 and BRCA2) and several Rad51 paralogues, but the exact mechanisms that underlie this process are only partially understood." (PMID 28471392, 2017). "The synthetic toxicity observed in the FAN1/BRCA2 double knock-down cells and the aggravated genomic instability of BRCA2-depleted cells expressing the FAN1 PIP*, UBZ* or ND mutants suggests that inhibition of FAN1 function in BRCA-deficient cancers may cause cell lethality." (PMID 29051491, 2017). "The identification of USP21 as a modulator of BRCA2 stability in HCC is, thus, expected to have important implications for both tumor growth and cancer therapy." (PMID 28743957, 2017). "Many other cancer-related genes show distinct alternative splicing profiles in cancers, including BRCA1, BRCA2, MDM2, KLK3 (also named prostate-specific antigen, PSA), and fibroblast growth factor receptors (FGFRs)." (PMID 28257090, 2017). "Switching on and off of an array of genes such as BRCA1, BRCA2, Akt1, ERCC1 and ABCB1 were identified to modulate sensitivity toward chemotherapy in cancer patients." (PMID 27980217, 2017). "In a separate line of investigation, RAD52 was identified as essential for viability of cancer cells with defects in various HR proteins including BRCA1, BRCA2, and partner and localizer of BRCA2 (PALB2)." (PMID 29145865, 2017). "However, the uncomplicated co-segregation pattern seen in BRCA1 and BRCA2 families, where (almost) all BC patients carry the predisposing mutation and where mutation carriers have a high risk to develop cancer (typical for high penetrant monogenic diseases), is not found in CHEK2 families." (PMID 28649653, 2017). "Detailed personal and family history of cancer was reported for 31 BRCA1 and 25 BRCA2 patients from those with available records." (PMID 27069714, 2016). "Some important cancer genes, such as PIK3CA, BRCA1, BRCA2, and ERBB2, show a mixture of amplifications and deletions." (PMID 27556158, 2016). "Various cancer-related genes were also differentially expressed significantly, including BRAF, BRCA2, VEGFA, VEGFB, RET, PIK3CA, CTNNB1 and GNAS." (PMID 27350898, 2016). "These genes participate either in DNA repair and checkpoint control, apoptosis or in the regulation of cell proliferation, adding other crucial targets for cancer progression besides BRCA1 and BRCA2 dependent DNA repair." (PMID 26979459, 2016). "Non-cancer, BRCA2-positive HK-2 kidney proximal tubule epithelial cells were treated with either control ASO or BRCA2 ASO followed by olaparib." (PMID 26959114, 2016). "BRCA2 does not mediate BER and, therefore, it is unlikely that, by targeting BRCA2 (which involves DNA repair pathways other than BER), cancer cells would be sensitized to a drug that requires BER for its toxicity." (PMID 26579709, 2015). "The FHIT, BRCA2 and MLH1 expression levels were identified to be significantly lower in the cancer tissues from OCFH + patients." (PMID 25436004, 2015). "When the sera from cancer patients were tested for the presence of autoantibodies to PARP1 and BRCA1/BRCA2, the autoantibody responses slightly decreased and the positive autoantibody reactions varied from 0% to 50.0%." (PMID 25865228, 2015). "Such systems with excess BRCA2 present may not be sensitive enough to detect subtle inefficiencies imparted by partial deletions of a functional domain, such as might be expected to lead to low-penetrance predisposition to cancer." (PMID 26455428, 2015).